LMNA (lamin A/C)
Diseases named in the same sentence as LMNA in open-access papers (continued):
Sharing a sentence is not in itself a finding about the gene and the disease.
Myocardial fibrosis (5 papers, 2011 to 2025). "The identification of LMNA p.(Asp576ThrfsTer124) as a pathogenic variant associated with sudden death and severe myocardial fibrosis provides a large animal model of a cardiac laminopathy." (PMID 37925523, 2023). "There is also a large body of evidence from human and mouse studies that LMNA variants can cause myocardial fibrosis and conduction system disturbances similar to what was seen in the NSDTR." (PMID 37925523, 2023). "In our study, 88% of LMNA mutation carriers had typical myocardial fibrosis, predominantly mid-myocardially in the basal septum." (PMID 21689390, 2011). "The main purpose of this study was to characterise myocardial fibrosis, regional wall motion abnormalities, ventricular dilatation, longitudinal LV systolic function and global function with LGE CMR in asymptomatic or mildly symptomatic carriers of LMNA mutations causing DCM." (PMID 21689390, 2011).
sudden cardiac death (5 papers, 2019 to 2025). "A mutation in the genes for lamin A/C (LMNA), desmoplakin (DSP) producing gene, sodium voltage-gated channel alpha subunit 5 (SCN5A) gene, and filamin C (FLNC) are genetic markers associated with DCMs that caused a higher risk in sudden cardiac death (SCD) related to malignant arrhythmias." (PMID 38975458, 2024).
type 2 diabetes (5 papers, 2018 to 2021). "This strategy, applied to the gene encoding A-type lamins (LMNA), revealed unexpectedly high frequencies of disease-causing LMNA alleles in specific ethnic groups, and linked a specific missense variant to type 2 diabetes." (PMID 31024910, 2019). "In addition, mutations in LMNA and ZMPSTE24 in patients lead to metabolic dysfunction, including type 2 diabetes and hepatic steatosis." (PMID 29484800, 2018).
colorectal cancer (4 papers, 2020 to 2023). A primary or metastatic malignant neoplasm that affects the colon or rectum. "It is possible that lamin A/C expression in colorectal cancer causes these cancer cells to become more stem cell-like, therefore, leading to an increase in mortality found in lamin A/C expressing colorectal cancers." (PMID 33316938, 2020). "Moreover, lamin-A/C is expressed in colonic stem cells and the ectopically expressed lamin-A colorectal cancer cell line SW480 shows enhanced morphological changes and invasive or motile properties." (PMID 37250905, 2023). "Furthermore, lamin A/C is overexpressed in colorectal cancers, where it correlates with poor prognosis, and overexpressing GFP-lamin A in colorectal cancer cells increases cell motility." (PMID 37219077, 2023).
glioma (4 papers, 2020 to 2025). A benign or malignant brain and spinal cord tumor that arises from glial cells (astrocytes, oligodendrocytes, ependymal cells). "Our data align with this finding, indicating that PRKDC and LMNA expression in the glioma stem cell compartment contribute to TMZ resistance in GBM." (PMID 41271669, 2025). "Of these TFGs, the role of TCF12, RUNX1T1, and LMNA in gliomas is still unclear and needs further investigation." (PMID 32695826, 2020). "LMNA expression was negatively correlated with survival in recurrent GBM, according to the GlioVis Chinese Glioma Genome Atlas dataset." (PMID 41271669, 2025). "These cells expressing LMNA, PRKDC, and PARP1 transcripts are molecularly more dedifferentiated glioma stem-like cells, specifically OPC-like cells." (PMID 41271669, 2025).
heart-hand syndrome (4 papers, 2016 to 2021). Heart-hand syndrome refers to a group of congenital disorders characterized by malformations of the upper limbs and heart. "Given that the patient's clinical diagnosis was heart-hand syndrome, we screened the TBX5, SALL4, and LMNA genes, but no deleterious variation was found." (PMID 34485408, 2021).
hepatocellular carcinoma (4 papers, 2020 to 2023). A malignant tumor that arises from hepatocytes. "For example, some evidence supports the function of LMNA as an oncogene in gastrointestinal tract tumors, prostate cancer (PC), hepatocellular carcinoma (HCC), and metastatic colorectal cancer (CRC)." (PMID 36552752, 2022). "We next engineered PLC/PRF/5 and sk-Hep1 cell lines with LMNA knockout using CRISPR/Cas9 to further explore the role of crotonylation of lamin A in hepatocellular cancer cells, and the LMNA-KO cells were marked as LMNA-/-." (PMID 35977926, 2022). "LMNA functions as an oncogene in many cancer cell types, especially in hepatocellular carcinoma." (PMID 37671046, 2023). "The role of the LMNA gene in the development and progression of hepatocellular carcinoma (HCC) and the associated molecular mechanism is not yet clear." (PMID 32896989, 2020).
hypertriglyceridemia (4 papers, 2012 to 2024). A laboratory test result indicating elevated triglyceride concentration in the blood. "LMNA codon 482 mutations were associated with specific metabolic features, particularly severe hypertriglyceridemia and lower HDL-c levels." (PMID 38887266, 2024).
Infertility (4 papers, 2013 to 2024). "LMNA (Lamin A/C), a deficiency of which is associated with infertility in women was down-regulated in the CT and TC groups while VIM, a mesenchymal intermediate filament was up-regulated in the CT group." (PMID 23791816, 2013). "Especially, it has been found that proteins LMNA and GPX4 are associated with diseases such as genetic disorder, embryo death, and infertility (p < 0.05)." (PMID 38561386, 2024). "In a series of 14 women with FPLD2, carrying the LMNA p.Arg482 variant, infertility was reported in 28% of cases." (PMID 35440056, 2022). "BAX, LMNA, and WFS1 were associated with an infertility-related condition in DisGeNET database." (PMID 31694346, 2019).
leukemia (4 papers, 2011 to 2025). A malignant (clonal) hematologic disorder, involving hematopoietic stem cells and characterized by the presence of primitive or atypical myeloid or lymphoid cells in the bone marrow and the blood. "One mechanism of lamin A/C deregulation in hematological malignancies is the epigenetic silencing of LMNA gene by CpG island promoter hypermethylation which results in the loss of A‐type lamins expression in leukemias and lymphoma." (PMID 39866838, 2025). "This reduced expression of LMNA has also been observed in leukemia and lymphoma, often associated with epigenetic silencing through CpG island promoter hypermethylation." (PMID 38731097, 2024). "The loss of LMNA/C expression has been observed in breast cancer, lung cancer, leukemia, and lymphoma, while its up-regulation has been noted in prostate and colorectal cancer." (PMID 38731097, 2024). "However, the expression of LMNA/C transcript variants in leukemia remains unexplored." (PMID 38731097, 2024). "For example, many cancer types present with alterations in lamin A/C, which is downregulated in lymphoma, leukemia, osteosarcoma, breast, and ovarian cancer cells, and upregulated in prostate cancer and glioblastoma multiforme." (PMID 39866838, 2025). "In our study, we observed a downregulation of LMNA and LMNC transcript variants in leukemia, particularly in AML." (PMID 38731097, 2024). "Notably, the ratio of LMNC to LMNA mRNA is notably elevated in AML, suggesting its potential as a diagnostic marker for this type of leukemia." (PMID 38731097, 2024).
Malouf syndrome (4 papers, 2018 to 2025). "Mutations in LMNA gene are identified in a wide variety of disorders, so-called laminopathies, which include HGPS, RD, MADA, EDMD2, atypical progeria syndrome, and Malouf syndrome." (PMID 32479501, 2020).
muscle disorders (4 papers, 2013 to 2023). "In summary, we report a targeted genetic analysis and segregation of variants in families, looking for additional rare variants in other genes than LMNA, which could explain the phenotypic differences in LMNA-related muscular diseases." (PMID 37035729, 2023). "Curiously, patient 14, diagnosed with EDMD and carrying the same variant p.Arg249Trp, showed a different phenotype possibly due to an unidentified alteration, reinforcing the targeted genetic analysis not only limited to the LMNA gene in patients diagnosed with LMNA-related muscular diseases." (PMID 37035729, 2023). "Again, numerous mutations in LMNA gene lead to different types of myopathies or muscle disorders in which muscle fibres do not stretch and relax normally resulting into different symptomatic diseases." (PMID 24386194, 2013). "Our study shows similar percentages of LMNA-related muscular diseases (EDMD, 50%; L-CMD, 42%; LGMD1B, 8%)." (PMID 37035729, 2023).
prostate carcinoma (4 papers, 2011 to 2024). A carcinoma that arises from epithelial cells of the prostate gland. "Interestingly, downregulation of lamin A/C appears to be an early event in prostate carcinogenesis, while impairment of the remaining NE proteins analyzed is a later step in prostate cancer evolution and is a hallmark of metastatic prostate cells." (PMID 39115711, 2024). "From that gene set we chose two genes, SATB1 and LMNA, for further assessment as potential biomarkers of high-risk prostate cancer because both genes repositioned in a single high-risk T3 stage cancer, but not in two intermediate risk T2 cancers, or a low risk T2 cancer." (PMID 31681438, 2019). "Positioning patterns for SATB1 and LMNA by prostate cancer subgroups." (PMID 31681438, 2019). "Rather than expression levels, the positioning of both the LMNA gene and lamin A/C protein have been shown to be altered in prostate cancer." (PMID 33316938, 2020).
valvular heart disease (4 papers, 2025). "Elucidating the mechanism by which LMNA p.Glu262Val specifically affects cardiac heart valves is likely to provide insight about the pathogenesis of Mendelian forms of valvular heart diseases and may help guide the development of therapies." (PMID 40783787, 2025).
ventricular tachycardia (4 papers, 2012 to 2025). A disorder characterized by an electrocardiographic finding of three or more consecutive complexes of ventricular origin with a rate greater than a certain threshold (100 or 120 beats per minute are commonly used). "Eva Cabrera-Borrego reported that ACM patients carrying LMNA gene mutations had the highest recurrence rate of ventricular tachycardia in their study; therefore, continued close follow-up of the proband is needed." (PMID 40709201, 2025). "The pathogenic variant of c.1526del p.P509Lfs*39 was a frameshift deletion located at exon 9 of LMNA chr1:156137145 and causes severe right atrial enlargement, sick sinus syndrome, atrial standstill, ventricular tachycardia, and bicuspid aortic valve malformation." (PMID 37465451, 2023).
atypical Werner syndrome (3 papers, 2013 to 2024). A heterogeneous group of cases that are clinically diagnosed as Werner syndrome (WS) but do not carry WRN gene mutations. "One subset of adult-onset progeroid syndromes, referred to as atypical Werner syndrome, is caused by mutations in the LMNA gene, which encodes a class of nuclear intermediate filaments, lamin A/C." (PMID 23847654, 2013).
colon cancer (3 papers, 2011 to 2023). "LMNA was found to be expressed in colon cancer and its expression level positively associates with colon tumor progression and the risk of death." (PMID 21448288, 2011). "Lamin A/C, a protein known to be involved in colon cancer, interacts with S100A6, which also provides indirect evidence that S100A6 is involved in colon cancer." (PMID 37670392, 2023).
COVID-19 (3 papers, 2021 to 2022). A disease caused by infection with severe acute respiratory syndrome coronavirus 2. "GSEA of the COVID-19-related gene sets indicated that three genes namely DYNC1H1, LMNA, and DCTN1 were downregulated in human bronchial epithelial cells in COVID-19 after 24hr of infection (GSE17400)." (PMID 34832615, 2021).
gastric cancer (3 papers, 2009 to 2022). A primary or metastatic malignant neoplasm involving the stomach. "The low expression of lamin A/C mRNA and protein observed in gastric carcinoma suggests that loss of lamin A/C involves in the development of human gastric carcinoma." (PMID 19144202, 2009). "For instance, immunohistochemistry showed decreased expression of LMNA and LMNB1 in 7/8 primary gastric cancers and 6/8 gastric cancers, respectively." (PMID 36589746, 2022).
Hypertension (3 papers, 2011 to 2024). The presence of chronic increased pressure in the systemic arterial system. "Arterial hypertension has also been reported occasionally in carriers of LMNA mutations." (PMID 37303410, 2023).
liver cancer (3 papers, 2015 to 2022). An epithelial or non-epithelial malignant neoplasm that arises from the liver. "We then took an intersection of the Kcr proteins identified in liver cancer tissue quantitative analysis and hypoxic cell lines: CAT, S100A8, EEF2, and LMNA were co-identified." (PMID 35977926, 2022).
rigid spine syndrome (3 papers, 2018 to 2024). "Differentiation from other early-onset conditions involving rigid spine syndrome caused by SELENON, FHL1, LMNA, and others is crucial." (PMID 39468638, 2024).
acute lymphoblastic leukemia (2 papers, 2024). Leukemia with an acute onset, characterized by the presence of lymphoblasts in the bone marrow and the peripheral blood. "In B cells, PRDM16 and DNMT3A for AML, PDCD1LG2 for Hodgkin’s lymphoma, LMNA for spritzed tumor, and BCL11B for T-cell acute lymphoblastic leukemia (T-ALL) harbored DMPs for HIV infection." (PMID 38466776, 2024).
Barth syndrome (2 papers, 2024 to 2025). Barth syndrome (BTHS) is an inborn error of phospholipid metabolism characterized by dilated cardiomyopathy (DCM), skeletal myopathy, neutropenia, growth delay and organic aciduria. "Neuromuscular disorders most frequently associated with LVNC include Barth syndrome, mitochondrial disorders, myotonic dystrophy, Holt-Oram syndrome, dystrobrevinopathy, and Emery–Dreifuss muscular dystrophy, particularly those involving LMNA mutations." (PMID 39407735, 2024).
brachydactyly (2 papers, 2018 to 2021). A disease characterized by the presence of brachydactyly, including syndromic and non-syndromic forms. "Here, we performed reduced representation bisulfite sequencing on ten pairs of fibroblasts and their induced pluripotent stem cell (iPSC) derivatives from two families with DCM due to distinct LMNA mutations, one of which also induces brachydactyly." (PMID 34246298, 2021). "The objective of this study is to understand the epigenetic mechanisms that play a role in both early developmental phenotypes (brachydactyly) and late-onset conditions (DCM) that arise due to LMNA mutations." (PMID 34246298, 2021). "To do so, we studied two families with distinct LMNA mutations, a heterozygous splice-site mutation causing DCM and a heterozygous missense mutation displaying both DCM and brachydactyly, similar to heart–hand syndrome (HHS) IV." (PMID 34246298, 2021).
dilated cardiomyopathy 1A (2 papers, 2016 to 2018). "LMNA mutations have also been implicated in other myopathies, including limb girdle muscular dystrophy type 1B (LGMD1B) and dilated cardiomyopathy type 1A (DCM1A)." (PMID 29861492, 2018).
dysferlinopathy (2 papers, 2018 to 2024). "Moreover, we observe significant associations between the protein expression of ANXA1, ANXA2, ANXA4, ANXA5, LMNA, PYGM, and the extent of histopathologic changes in muscle biopsies from patients with dysferlinopathy, validated through immunoblotting and immunofluorescence assays." (PMID 39350328, 2024).
embryonal carcinoma (2 papers, 2015 to 2020). A non-seminomatous malignant germ cell tumor characterized by the presence of large germ cells with abundant cytoplasm resembling epithelial cells, geographic necrosis, high mitotic activity, and pseudoglandular and pseudopapillary structures formation. "Retinoic acid was reported to enhance the LMNA promoter activity in murine P19 embryonal carcinoma cells; on the other hand, LMNA downregulation has been also described following ATRA treatment in human alveolar carcinoma and in HL-60 cells." (PMID 26359359, 2015). "Moreover, a retinoic acid (RA) responsive element has been found in the LMNA promoter of P19 embryonic carcinoma cells, and RA reduces lamin A/C expression in HL-60 cells and human monocyte-derived myeloid cells." (PMID 32854281, 2020).
familial cardiomyopathy (2 papers, 2010 to 2015). An instance of cardiomyopathy that is caused by an inherited modification of the individual's genome. "Two hot spots (TNNI3-p.Arg145Gly, and LMNA-p.Arg190Trp) and double (LMNA-p.Arg190Trp plus MYH7-p.Arg1045His) heterozygous mutations were found to be highly correlated with familial cardiomyopathy." (PMID 26199943, 2015). "LMNA Δ303 or LMNA D596N each independently are known to cause dominantly inherited familial cardiomyopathy." (PMID 21179469, 2010). "Many nonsynonymous variations were detected in the familial cardiomyopathy patients and per nonsynonymous variation in coverage of more than 30x, including three pathogenic heterozygotic mutations (TNNI3, c.433C>G, p.Arg145Gly; LMNA, c.568C>T, p.Arg190Trp; and MYH7, c.3134G>A, p.Arg1045His)." (PMID 26199943, 2015).
focal segmental glomerulosclerosis (2 papers, 2023 to 2024). A renal disorder characterized by sclerotic lesions in the glomeruli. "Germline LMNA mutations carried across generations in focal segmental glomerulosclerosis (FSGS) patients also points to a physiological role of LMNA in the maintenance of glomerular structure and function." (PMID 38858654, 2024).
HCMV infection (2 papers, 2009 to 2024). "UL97 mimicry of a CDK for phosphorylation of lamin A/C explains at least part of this viral enzyme's role in HCMV infection." (PMID 19165338, 2009). "From these results, we conclude that there is UL97-dependent phosphorylation of lamin A/C at Ser22 during HCMV infection." (PMID 19165338, 2009).
Hepatic steatosis (2 papers, 2018 to 2023). Steatosis is a term used to denote lipid accumulation within hepatocytes. "Additionally, LMNA mutations lead to partial lipodystrophy, a condition associated with insulin‐resistant diabetes, hypertriglyceridemia, and hepatic steatosis." (PMID 29484800, 2018).
herpesvirus infections (2 papers, 2020 to 2023). "In addition, we were able to identify and confirm a specific serine residue in lamin A/C that is phosphorylated via US3, leading to new insights into lamin phosphorylation in herpesvirus infections." (PMID 33167340, 2020).
HIV-1 infection (2 papers, 2023 to 2024). The type species of lentivirus and the etiologic agent of acquired immunodeficiency syndrome (AIDS). "Upregulated C1QA, CD163, and CXCL16 and downregulated LMNA and CLU were identified as age-associated genes tied to HIV-1 infection." (PMID 38399364, 2024). "For example, IL-1α, IL-10, CCL2, LMNA, and VCAM1, the target genes identified in this study, have been reported to be associated with HIV-1 infection and pathogenesis." (PMID 38110484, 2023).
idiopathic cardiomyopathy (2 papers, 2018). A disease of the heart muscle or myocardium proper whose cause is unknown. "Consistent with our finding, mutations in human LMNA result in dominant dilated, hypertrophic, and idiopathic cardiomyopathy." (PMID 29575479, 2018). "By an age of 60 years, 55% of LMNA mutation carriers die of cardiovascular death or receive a heart transplant, compared with 11% of patients with idiopathic cardiomyopathy without LMNA mutation." (PMID 29619865, 2018).
Left bundle branch block (2 papers, 2019 to 2024). A conduction block of the left branch of the bundle of His. "One previously GWAS-linked gene (SCN5A) and 3 novel genes (LMNA, SMAD6, HSPB9) were identified for atrioventricular and left bundle branch block (ICD10 code I44)." (PMID 38390584, 2024).
lipoma (2 papers, 2024 to 2025). A benign, usually painless, well-circumscribed lipomatous tumor composed of adipose tissue. "The presence of lipomas is common, particularly in cases associated with variants of LMNA, MFN2, or LIPE." (PMID 40452043, 2025).